CRELD2 (CRELD disulfide isomerase 2)
Description:
Protein disulfide isomerase (By similarity). Might play a role in the unfolded protein response (By similarity). May regulate transport of alpha4-beta2 neuronal acetylcholine receptor.
Synonyms: MGC11256
Tractability: Antibody: UniProt predicts a signal peptide or a membrane-spanning region. PROTAC: ubiquitination databases record sites on it; its protein half-life has been measured.
Gene: Protein-coding gene on chromosome 22 (49,917,989 to 49,927,544, forward strand). Ensembl gene ENSG00000184164.
Subcellular location: Endoplasmic reticulum
Gene Ontology:
Molecular function: protein binding; protein disulfide isomerase activity; calcium ion binding
Cellular component: endoplasmic reticulum; extracellular matrix; extracellular region; Golgi apparatus
Genetic constraint (gnomAD): Loss-of-function variants: 29 observed, 35.33 expected, observed/expected ratio (o/e) 0.82, 90% interval 0.61 to 1.12. The upper end of that interval is the gene's LOEUF score, 1.12, which puts it in group 4 of 6, group 1 being the genes least tolerant of losing a copy. Missense variants: 429 observed, 418.05 expected, observed/expected ratio (o/e) 1.03, 90% interval 0.95 to 1.11. Synonymous variants: 201 observed, 174.41 expected, observed/expected ratio (o/e) 1.15, 90% interval 1.03 to 1.29.
Homologues: Orthologues: chimpanzee CRELD2 (99% identical), macaque CRELD2 (92% identical), dog CRELD2 (77% identical), pig CRELD2 (76% identical), rat Creld2 (76% identical), guinea pig CRELD2 (75% identical), mouse Creld2 (75% identical), tropical clawed frog creld2 (56% identical), zebrafish creld2 (50% identical), Caenorhabditis elegans T25C12.3 (21% identical), Caenorhabditis elegans ZK1193.2 (20% identical), Caenorhabditis elegans apx-1 (18% identical), and 5 more. Paralogues in human: CRELD1 (49% identical), CD93 (26% identical), FBLN7 (20% identical), DLL3 (19% identical), CD248 (18% identical), DLK2 (18% identical), WIF1 (17% identical), CLEC14A (12% identical).
Diseases named in the same sentence as CRELD2 in open-access papers:
CRELD2 is named in the same sentence as 49 diseases in open-access papers, as found by Europe PMC text mining. Sharing a sentence is not in itself a finding about the gene and the disease. The quoted sentences say what the papers report.
breast carcinoma (6 papers, 2021 to 2025). "This study also found a significant association between high CRELD2 expression and decreased survival in breast cancer patients, with particular relevance to the triple-negative subtype." (PMID 39869369, 2025). "- CRELD2 expression upregulated in samples of invasive breast carcinoma;- High CRELD2 expression is associated with progressive human breast cancer." (PMID 36936176, 2023). "Interestingly, the work showed that activation of this signaling axis led to CRELD2 enrichment in the secretome of breast cancer cells and CRELD2‐mediated education of cancer‐associated fibroblasts to a tumor‐promoting form." (PMID 34532864, 2021). "CRELD2 also drives tumor progression and is necessary for ROCK-induced education of cancer-associated fibroblasts to a tumor-promoting phenotype in breast cancer and cutaneous squamous cell carcinoma." (PMID 40821803, 2025). "We have previously demonstrated that CRELD2 secretion enhances the tumor‐promoting characteristics of CAFs in breast cancer." (PMID 38979935, 2024). "Consistently, CRELD2 has been shown to be transcriptionally regulated by ATF4 in breast cancer." (PMID 40821803, 2025). "Here, we show that consistent with our observations in breast cancer, enhanced ROCK activity and consequent production of CRELD2 is associated with the recruitment and tumor‐promoting polarization of cancer‐associated fibroblasts in cutaneous squamous cell carcinoma." (PMID 38979935, 2024). "Interestingly, CRELD2 appears to be principally produced by squamous epithelium, which is consistent with our observation that CRELD2 is secreted by mammary tumor cells of epithelial origin in breast cancer." (PMID 38979935, 2024). "Nevertheless, these data are consistent with the notion that CRELD2 upregulation in cSCCs may be involved in the recruitment of fibroblasts into the microenvironment as previously demonstrated in the case of breast cancers." (PMID 38979935, 2024). "Recent findings using a mouse model revealed that stress sensors increase CRELD2 protein synthesis, promoting tumor growth and proliferation by amplifying CAF activity in breast cancer—particularly in the triple-negative subtype." (PMID 39869369, 2025). "-ROCK activation in mammary cancers yielded a tumour-promoting fibroblast phenotype through paracrine CRELD2;- ROCK activation in mammary cancers induced ATF4-regulated Creld2 transcription." (PMID 36936176, 2023). "They found that Creld2 is regulated by PERK-modulated ATF4 via a putative C/ebp-Atf response element (CARE) in the promoter sequences of Creld2, and CRELD2 depletion suppresses tumor progression, indicating that the paracrine ROCK-PERK-ATF4-CRELD2 axis promotes breast cancer progression." (PMID 36936176, 2023). "A factor shared between MP2, MP3, and MP4, which has not been mentioned yet, is CRELD2 (Cysteine-rich with EGF-like domain protein 2), a factor regulated by the ROCK-PERK-ATF4 axis with the potential to promote tumor progression in breast cancer." (PMID 38306361, 2024).
Obesity (4 papers, 2019 to 2023). Accumulation of substantial excess body fat. "Top downregulated genes included those previously associated with diabetes and obesity, such as Manf and Creld2 that facilitate protein folding, and Igfbp3 and Igfbp7, two structurally similar proteins that regulate the bioavailability of IGFs and insulin." (PMID 36988733, 2023). "By comparing regulators that were identified for lean, obese, and merged islet expression data, Cck, C1ql3, Serpina7, Creld2, Svop, Smoc1, Tgfβ3, and Serpini1 were identified to affect islet function in obesity." (PMID 31300714, 2019). "However, information on the changes in circulating CRELD2 levels in ER stress-related diseases, including diabetes, obesity, inflammation, NAFLD, CVDs, kidney diseases, and cancer, is still lacking." (PMID 36936176, 2023). "Therefore, the results of proteomic analyses indicate that the ER proteins such as RRBP1, CRELD2 and PDIA3 in the exosomes were differentially regulated by the obesity-associated OS condition in the caput epididymis and may indeed affect sperm maturation." (PMID 36411474, 2022). "Thus, in the current study, the differential expression of RRBP1, CRELD2 and PDIA3 in exosomes may indeed attribute to obesity-induced ER stress." (PMID 36411474, 2022).
invasive breast carcinoma (3 papers, 2021 to 2025). A carcinoma that infiltrates the breast parenchyma. "The same study demonstrated higher CRELD2 expression levels in invasive breast carcinomas compared to normal tissue and showed that tumor progression was arrested when CRELD2 levels were reduced." (PMID 39869369, 2025).
multiple epiphyseal dysplasia (3 papers, 2010 to 2023). Multiple epiphyseal dysplasias (MED/EDMs) are characterized by epiphyseal anomalies causing joint pain early in life, recurrent osteochondritis and early arthrosis. "Interestingly, the mouse model for multiple epiphyseal dysplasia, which specifically expresses a mutation in matrilin-3, was reported to induce CRELD2 mRNA expression and other ER-stress inducible genes as the symptoms progressed." (PMID 21106106, 2010). "The function of Creld2 is unknown, however it was shown to be highly upregulated, along with Armet, in a Matn3 mutant model of multiple epiphyseal dysplasia." (PMID 21935428, 2011).
chondrodysplasia (2 papers, 2013 to 2023). "In this study, we used a variety of cell and mouse models of chondrodysplasia to determine the genotype-specific expression profiles of Armet and Creld2." (PMID 23956175, 2013).
hepatocellular carcinoma (2 papers, 2022 to 2023). A malignant tumor that arises from hepatocytes. "Some studies confirmed Creld2 is the crucial gene and a viable therapeutic target for hepatic steatosis and hepatocellular carcinoma." (PMID 36120318, 2022). "Additionally, CRELD2 gene and protein expressions are significantly upregulated in hepatocellular carcinoma (HCC) than in non-tumor tissues, and CRELD2 is associated with poor overall survival and disease-free survival in HCC." (PMID 36936176, 2023).
acute kidney injury (1 paper, 2023). Sudden and sustained deterioration of the kidney function characterized by decreased glomerular filtration rate, increased serum creatinine or oliguria. "Additionally, CRELD2 is rapidly secreted when renal cells are subjected to ER stress in mouse models of podocyte ER stress-induced nephrotic syndrome (NS) and Tm- or I/R-induced acute kidney injury (AKI)." (PMID 36936176, 2023).
endometrial cancer (1 paper, 2025). Primary or metastatic malignant neoplasm involving the endometrium (mucous membrane that lines the endometrial cavity). "Data from the Human Protein Atlas database further underscore the complex prognostic role of CRELD2, identifying it as an unfavorable marker in kidney cancer but a favorable marker in endometrial cancer." (PMID 39869369, 2025).
heart failure (1 paper, 2024). Inability of the heart to pump blood at an adequate rate to meet tissue metabolic requirements. "Creld2-deficient mice and wild-type mice treated with a CRELD2-neutralizing antibody showed impaired de novo microvessel formation in the infarct border zone and developed severe postinfarction heart failure." (PMID 39196188, 2024).
hepatic cancer (1 paper, 2025). "CTSA, CRELD2, MAPK10, and other specific genes are associated with the Ras and MAPK signaling pathways, which have been implicated in tumorigenesis and metastasis of hepatic cancer." (PMID 40901642, 2025).
hypertriglyceridemia (1 paper, 2025). A laboratory test result indicating elevated triglyceride concentration in the blood. "This suggests a potential link between CRELD2 and hypertriglyceridemia through the regulation of Fasn." (PMID 40072100, 2025).
Insulin resistance (1 paper, 2023). Increased resistance towards insulin, that is, diminished effectiveness of insulin in reducing blood glucose levels. "- Creld2-/- mice gained less weight;- Creld2-/- mice developed insulin resistance;- Creld2-/- livers contained fewer lipids;- Creld2-/- livers exhibited more apoptosis- Creld2-/- livers showed similar UPR activation." (PMID 36936176, 2023). "Their results showed that Creld2-/- mice exhibited a reduction in body weight under both a chow diet and high-fat diet (HFD) compared to their controls but developed insulin resistance." (PMID 36936176, 2023).
melanoma (1 paper, 2022). A malignant, usually aggressive tumor composed of atypical, neoplastic melanocytes. "For the level of mRNA expression in the TCGA database and melanoma cell lines, SLC39A14, PSMB4, CRELD2, CDKN2A and TIMP1 were higher in SKCM tissues than in normal skin tissues, and NDRG1, ATF3, and JUND had an opposite trend." (PMID 36226170, 2022).
metabolic syndrome (1 paper, 2025). A cluster of metabolic risk factors for CARDIOVASCULAR DISEASES and TYPE 2 DIABETES MELLITUS. "CRELD2 is an ER stress inducible chaperone molecule that has been implicated in metabolic syndromes." (PMID 40072100, 2025). "The modulation of Fasn by liver CRELD2 may play a crucial role in the dyslipidemia associated with NAFLD-NASH phenotypes, warranting further investigation in future studies." (PMID 40072100, 2025).
Nephropathy (1 paper, 2022). A nonspecific term referring to disease or damage of the kidneys. "Since DR is usually accompanied by other diabetic complications, such as nephropathy and neuropathy, the mutant genes, such as PTPRF and CRELD2 were linked with more than one type of complication, including DR." (PMID 36035153, 2022).
neuroblastoma (1 paper, 2018). Neuroblastoma (NB) is the most common solid, extracranial childhood tumor. "On the other hand, we first identified CRELD2 as a novel ER stress-inducible gene using microarray analysis of Tg-treated mouse neuroblastoma cell-line, Neuro2a3, and have been employing this Neuro2a cells to elucidate several ER stress gene expression (e.g., MANF, Chac1 and GADD153) in detail." (PMID 30111858, 2018).
Osteopenia (1 paper, 2023). Osteopenia is a term to define bone density that is not normal but also not as low as osteoporosis. "recently found that mice with cartilage-specific deletion of Creld2 had a chondrodysplasia-like phenotype with abnormal cartilage growth plates; however, the deletion of Creld2 in bone results in osteopenia, with a low bone density and altered trabecular architecture." (PMID 36936176, 2023).
osteopetrosis (1 paper, 2022). Osteopetrosis, also known as marble bone disease, is a descriptive term that refers to a group of rare, heritable disorders of the skeleton characterized by increased bone density on radiographs. "We therefore propose that CRELD2 is a potential druggable target in osteoclast precursors which could modulate osteoclast differentiation and osteolysis in diseases characterised by defective osteoclast differentiation and/or function such as osteopetrosis and osteoporosis." (PMID 35974042, 2022).
prostate carcinoma (1 paper, 2025). A carcinoma that arises from epithelial cells of the prostate gland. "CRELD2 may also mediate tumor angiogenesis and serve as a novel androgen receptor target in prostate cancer." (PMID 39869369, 2025).
renal cell carcinoma (1 paper, 2023). "Among these, CRELD2 was one of the target genes whose expression was significantly associated with poor prognosis in patients with renal cell carcinoma by TCGA database analyses." (PMID 36936176, 2023).
skin aging (1 paper, 2023). The gradual irreversible changes in structure of skin that occur as a result of the passage of time.. "Two genes IRF4 and CRELD2 have been implicated in skin aging measurement." (PMID 37924108, 2023).
squamous cell carcinoma (1 paper, 2024). A carcinoma arising from squamous epithelial cells. "Taken together, these data suggest that CRELD2 may regulate the recruitment and tumor‐promoting polarization of CAFs and may therefore impact patient survival in squamous cell carcinoma." (PMID 38979935, 2024).
steatosis (1 paper, 2023). Increased lipid within the cytoplasm of cells. "Similarly, a sex dimorphism was also observed in aged mice, with only Creld2-/- males developing steatosis." (PMID 36936176, 2023). "Furthermore, they found an inverse correlation between serum concentrations of CRELD2 and Steatosis, Activity, and Fibrosis (SAF) scores in male patients." (PMID 36936176, 2023).
triple-negative breast carcinoma (1 paper, 2025). An invasive breast carcinoma which is negative for expression of estrogen receptor (ER), progesterone receptor (PR), and human epidermal growth factor receptor 2 (HER2). "This study aimed to determine the prognostic value of CRELD2 status on survival outcomes in triple-negative breast cancer (TNBC)." (PMID 39869369, 2025).
tumor (13 papers, 2007 to 2025). "ROCK (ROCK1, bSE = 4.5)-mediated selective activation of PERK signaling causes fibroblast reprogramming and tumor progression through a CRELD2 (bSE = 0.7)-dependent mechanism." (PMID 39335478, 2024). "In the metastatic patient group, CRELD2 status, CRELD2 expression percentage, body mass index, de novo metastasis, surgery for the primary tumor, Ki-67 level, tumor grade, T stage, and N stage were evaluated as risk factors for OS using univariate Cox regression analysis." (PMID 39869369, 2025). "For instance, abnormal glycosylation in tumor tissues facilitates CRELD2 secretion, promoting the progression of colorectal cancer." (PMID 40821803, 2025). "A recent study discovered that CRELD2-mediated disruption of tumor–stroma crosstalk presents a potential therapeutic target, emphasizing the importance of CRELD2 in patients with metastatic TNBC." (PMID 39869369, 2025). "Here we have adopted a correlative approach to demonstrate in patient samples, a strong association between CRELD2 expression and the recruitment of fibroblasts and the enhancement of CAF tumor‐promoting markers in cSCC." (PMID 38979935, 2024). "Depleting CRELD2 suppressed tumor progression, demonstrating that the paracrine ROCK-PERK-ATF4-CRELD2 axis promotes the progression of BC, with implications for cancer therapy." (PMID 39335478, 2024). "As previously shown in (tumor) cell lines, CRELD2 is weakly expressed under basal conditions but strongly induced and secreted during ER stress." (PMID 39196188, 2024). "CRELD2 was reported to be involved in a kidney disease induced by ER stress and tumor development mediated by the ROCK-PERK-ATF4 signaling pathway." (PMID 36411474, 2022). "The gene expression data form both the cell culture models and the clinical tumor samples suggest androgen-mediated stimulation of CRELD2 and DDT." (PMID 17553165, 2007). "Resting tumour cDC1s included cluster 5 enriched in transcripts involved in the unfolded protein response (UPR) such as Creld2, Hspa5, and Pdia6, as well as the clusters 2, 3 and 6 that expressed transcripts such as Fos, Jun, and Dusp1 and cluster 0 that expressed H2afz, Lyz2, Sub1." (PMID 40745918, 2025). "A recent study identified CRELD2 as a driver of tumor progression." (PMID 39869369, 2025). "As an ER-resident protein, CRELD2 may play a critical role in this adaptive response, potentially driving tumor progression and therapy resistance." (PMID 39869369, 2025). "CRELD2 protein expression in tumor tissue was determined by immunohistochemical staining (IHC)." (PMID 39869369, 2025). "Given that RHO‐ROCK signaling promotes tumor progression in cSCC, we therefore wondered whether CRELD2 has a role in cSCCs exhibiting ROCK activation and if so, whether this was associated with enhanced fibroblast infiltration in human patients." (PMID 38979935, 2024). "Similar to our observation that CRELD2 is retained in the ECM of the infarct region, CRELD2 has been detected in the tumor ECM where it may promote autocrine or paracrine effects." (PMID 39196188, 2024). "For example, in vitro studies revealed that CRELD2 expression significantly increased MB114 cell invasion and promoted a trend toward enhanced angiogenic sprouting, thereby suggesting that CRELD2 might be a mediator of tumor angiogenesis." (PMID 36936176, 2023). "Furthermore, we also observed a strong correlation between CRELD2 levels and those of the CAF marker S100A4, suggesting that CRELD2 may also be involved in establishing a tumor‐promoting CAF phenotype in cSCC." (PMID 38979935, 2024). "Particularly, the methylation of Derl3 and Herp was reduced in the tumor portion of older KOs, methylation of Creld2, Wfs, and Yod1 was not changed in the normal liver portion, and mRNA expression of Hrd1 and Yod1 was remarkably increased in both liver and tumor portions of KO with liver tumors." (PMID 24198826, 2013).
tumor (continued). "In the tumor bearing livers, the methylation of Derl3, Herp, and Yod1 was reduced in the tumor portion compared to the normal liver portion whereas the methylation of Creld2 or Wfs was not significantly changed in the tumor portion compared to the liver portion." (PMID 24198826, 2013).